DKK3 (dickkopf Wnt signaling pathway inhibitor 3)
Description:
Antagonizes canonical Wnt signaling by inhibiting LRP5/6 interaction with Wnt and by forming a ternary complex with the transmembrane protein KREMEN that promotes internalization of LRP5/6. DKKs play an important role in vertebrate development, where they locally inhibit Wnt regulated processes such as antero-posterior axial patterning, limb development, somitogenesis and eye formation. In the adult, Dkks are implicated in bone formation and bone disease, cancer and Alzheimer disease (By similarity).
Synonyms: REIC; RIG; CRRL
Tractability: Antibody: UniProt places it where antibodies can reach, with medium confidence; UniProt predicts a signal peptide or a membrane-spanning region; its Gene Ontology location is reachable by antibodies, with medium confidence.
Gene: Protein-coding gene on chromosome 11 (11,956,207 to 12,009,948, reverse strand). Ensembl gene ENSG00000050165.
Subcellular location: Secreted
Subcellular location (Human Protein Atlas): Vesicles; Cytosol; Nuclear bodies; Predicted to be secreted
Gene Ontology:
Molecular function: protein binding; co-receptor binding; receptor antagonist activity
Biological process: adrenal gland development; negative regulation of aldosterone biosynthetic process; negative regulation of canonical Wnt signaling pathway; negative regulation of cortisol biosynthetic process; negative regulation of DNA-templated transcription; anatomical structure morphogenesis; negative regulation of anti-Mullerian hormone signaling pathway; regulation of transforming growth factor beta receptor signaling pathway; negative regulation of Wnt signaling pathway
Cellular component: extracellular region
Genetic constraint (gnomAD): Loss-of-function variants: 25 observed, 36.57 expected, observed/expected ratio (o/e) 0.68, 90% interval 0.5 to 0.95. The upper end of that interval is the gene's LOEUF score, 0.95, which puts it in group 4 of 6, group 1 being the genes least tolerant of losing a copy. Missense variants: 376 observed, 436.26 expected, observed/expected ratio (o/e) 0.86, 90% interval 0.79 to 0.94. Synonymous variants: 180 observed, 175.05 expected, observed/expected ratio (o/e) 1.03, 90% interval 0.91 to 1.16.
Homologues: Orthologues: chimpanzee DKK3 (98% identical), macaque DKK3 (97% identical), dog DKK3 (86% identical), guinea pig DKK3 (85% identical), pig DKK3 (84% identical), mouse Dkk3 (82% identical), rabbit DKK3 (77% identical), rat Dkk3 (74% identical), tropical clawed frog dkk3 (43% identical), zebrafish dkk3b (35% identical), zebrafish dkk3a (31% identical).
Diseases named in the same sentence as DKK3 in open-access papers:
DKK3 is named in the same sentence as 213 diseases in open-access papers, as found by Europe PMC text mining. Sharing a sentence is not in itself a finding about the gene and the disease. The quoted sentences say what the papers report.
prostate carcinoma (48 papers, 2008 to 2025). A carcinoma that arises from epithelial cells of the prostate gland. "The relevance of increased MMP2 activity for prostate cancer cell invasion is underlined by the ability of the MMP2 inhibitor ARP100 to reduce the pro-invasive effects of DKK3-silenced WPMY-1 CM in PC3 cells." (PMID 29858602, 2018). "The loss of stromal Dkk-3 is therefore predicted to lead to further disruption of prostate architecture, increased proliferation and prostate cancer cell invasion." (PMID 29858602, 2018). "We have observed several positive interactions between DKK3 gene polymorphisms and the risk of prostate cancer in a Korean population for the first time." (PMID 26689513, 2015). "Despite these limitations, the present study provides the first evidence of an important and novel association between DKK3 polymorphisms and the risk for prostate cancer, so will be a basis for future study." (PMID 26689513, 2015). "We now investigated the suitability of Dkk-3 as a diagnostic biomarker for prostate cancer (PCa) in seminal plasma (SP)." (PMID 22071168, 2011). "The existence of such an association has been demonstrated in prostate cancer, in which expression of DKK3 was predominantly lost in high-grade prostatic tumours." (PMID 18826564, 2008). "A significant correlation between DKK3 downregulation and poor prognosis was reported in patients with cervical squamous cell carcinoma or gastric cancer, and DKK3 loss was significantly associated with higher Gleason scores in prostate cancer." (PMID 35205672, 2022). "In prostate cancer, Dkk-3 overexpression causes apoptosis through the activation of JNK signaling." (PMID 27827955, 2016). "In this study, we examined whether genetic variations in the DKK3 gene alter the risk of developing prostate cancer." (PMID 26689513, 2015). "Logistic regression analysis of DKK3 SNPs with the risk of prostate cancer in Korean Population." (PMID 26689513, 2015). "A total of 53 SNPs from the human DKK3 gene in 272 patients with prostate cancer and 173 control subjects were successfully genotyped to determine the potential association of the gene with the development of prostate cancer (Figure-1)." (PMID 26689513, 2015). "In this study, we epidemiologically investigated whether SNPs of the DKK3 gene were related to the risk and aggressiveness of prostate cancer for the first time." (PMID 26689513, 2015). "Here we investigated whether SNPs of the DKK3 gene were associated with the development of prostate cancer in a Korean cohort." (PMID 26689513, 2015). "We hypothesized that sequence variations in DKK3 are candidates for risk factors for development of prostate cancer and progression." (PMID 26689513, 2015). "We anticipate that patients' genomic data could be used in clinical practice to investigate associations between the risk of prostate cancer and polymorphisms in the DKK3 gene in the near future." (PMID 26689513, 2015). "We had investigated whether sequence variants within DKK3 gene are associated with the development of prostate cancer in a Korean study cohort." (PMID 26689513, 2015). "Hypomethylation of tumor suppressor genes, such as BTG2 and DKK3, in the tumor group results in decreased gene expression, contributing to prostate cancer proliferation." (PMID 40265030, 2025). "Clinical trials are underway to explore the potential of REIC/DKK-3 gene therapy for prostate cancer and liver cancer." (PMID 38201279, 2023). "Herein, we confirmed that DKK3 was inversely correlated with miR‐363‐3p in prostate cancer specimens." (PMID 35303365, 2022). "In benign prostatic hyperplasia (BPH) and prostate cancer, Dkk-3 increases ANGPT2 expression, a destabilizing factor that leads to the formation of vessel sprouting in the tumor microenvironment." (PMID 36497305, 2022). "One example of how DKK levels can vary according to the type of sample analyzed (where) is the case of DKK-3 in prostate cancer." (PMID 34451907, 2021).
prostate carcinoma (continued). "miR-95-3p, that was described upregulated in prostate carcinoma tissues, promoted cell proliferation, migration and invasion of cancerous cells through repressing DKK3 prostate." (PMID 34769207, 2021). "For instance, it has been shown that DKK-3, produced by benign stroma, increases the tumorigenicity of prostate cancer cells." (PMID 34884726, 2021). "Clinical trials using WNT receptor inhibitors include Ad5-SGE-REIC/Dkk3 for prostate cancer and MCLA-158 for metastatic colorectal cancer." (PMID 34771683, 2021). "In this study, we find that LINC00261-targeted GATA6 suppresses the proliferation, migration, invasion and angiogenesis of prostate cancer by promoting activation of DKK3." (PMID 33013201, 2020). "In prostate cancer cells, Dkk3 expression inhibited cell proliferation and tumor growth, induced apoptosis, and sensitized cells to doxorubicin by c-JNK activation, mitochondrial redistribution of Bax, or by triggering Bcl-2 hypoexpression." (PMID 33425757, 2020). "Meanwhile, adeno-Dkk3 gene delivery has been demonstrated to suppress tumor growth and the rate of invasion and metastasis of prostate cancer cells." (PMID 33425757, 2020). "In this study, we proved that DKK3 expression was reduced in prostate cancer cells compared with adjacent normal tissues." (PMID 33013201, 2020). "Consist with the previous study, treatment with downregulation of DKK-3 facilitated malignant phenotypes of prostate cancer cells, upregulating MMP-2 and MMP-9, and even reversed the effect caused by overexpression of LINC00261." (PMID 33013201, 2020). "The expression of DKK3 in prostate cancer cells was the lowest in LNCaP, which was consistent with the trend of LINC00261 expression." (PMID 33013201, 2020). "Further, it was noted that DKK3 mediated Wnt/β-catenin pathway and thereby suppressed in cellular processes in prostate cancer and hepatocellular carcinoma, incorporating with miRNA." (PMID 33013201, 2020). "Western blot analysis was conducted to assess the expression of DKK3 in all prostate cancer and normal cell lines." (PMID 33013201, 2020). "Given the limited effects of Dkk-3 induction on prostate cancer cell proliferation, it would be interesting to explore its effects when used in combination with other therapies." (PMID 29843383, 2018). "The inverse correlation between TGFBI and Dkk-3 in cancer was only observed in low Gleason score tumors, suggesting that regulation of TGFBI by Dkk-3 is less important in more advanced prostate cancer." (PMID 29858602, 2018). "Dickkopf-3 (Dkk-3), shown to inhibit TGF-β signaling, is downregulated in prostate cancer and upregulated in the stroma in benign prostatic hyperplasia, but the function of stromal Dkk-3 is unclear." (PMID 29858602, 2018). "Based on these studies, we have proposed that endogenous Dkk-3 plays a protective role in prostate cancer by limiting TGF-β/Smad/MMP signaling." (PMID 29858602, 2018). "We used immunohistochemistry to compare Dkk-3 levels in epithelial and stromal cells in cancer and benign tissue from 99 treatment-naive prostate cancer patients." (PMID 29858602, 2018). "Together, these observations provide support for using CRISPR-mediated induction of DKK3 as a potential therapeutic approach for prostate cancer and highlight complexities in Dkk-3 regulation of TGF-β signaling." (PMID 29843383, 2018). "Here, we show that treatment of PC3 prostate cancer cells with the DNA methyltransferase (DNMT) inhibitor decitabine demethylates the DKK3 promoter, induces DKK3 expression, and inhibits TGF-β/Smad-dependent transcriptional activity." (PMID 29843383, 2018). "There was an inverse correlation of TGFBI and Dkk-3 expression in prostate cancer, consistent with the increased levels of TGFBI observed upon DKK3 silencing in RWPE-1 cells." (PMID 29858602, 2018). "While ectopic expression of Dkk-3 leads to prostate cancer cell apoptosis, it is unclear if Dkk-3 has a physiological role in cancer cells." (PMID 29843383, 2018).
prostate carcinoma (continued). "In the DKK3/DKK3b-deficient, PC3 prostate cancer line, expression of DKK3b arrested cell proliferation of the at the G0/G1 phase of the cell cycle and led to the loss of DKK3b expressing cells by 24–36 h of induction." (PMID 28738084, 2017). "In humans, adenovirus-mediated REIC/Dkk-3 overexpression in various cancers, including prostate cancer, induces tumour specific apoptosis." (PMID 28599655, 2017). "A reporter assay in human prostate cancer cells that displayed suppressed AR signaling by SGTA showed recovery of AR signaling by REIC/DKK-3 expression." (PMID 26658102, 2016). "DKK3 down-regulation has been reported in endometrial cancer, lung cancer, gastrointestinal cancer, breast cancer, prostate cancer, and renal carcinomas." (PMID 26689513, 2015). "A total of 53 SNPs located in the DKK3 gene were genotyped in 272 patients with prostate cancer and 173 control subjects with BPH." (PMID 26689513, 2015). "We previously reported that REIC/Dkk-3-expressing adenovirus vector (Ad-REIC) induced endoplasmic reticulum (ER) stress and cancer-specific apoptosis in human prostate cancer." (PMID 24498395, 2014). "Ad-C-TSC showed remarkably higher expression levels of REIC/Dkk-3 than those by Ad-CMV in prostate cancer cells (PC-3 cells) and cervical cancer cells (HeLa cells)." (PMID 24526517, 2014). "We have been trying to develop a new gene therapeutic measure mainly against prostate cancer using an adenovirus carrying REIC/Dkk-3 cDNA." (PMID 24526517, 2014). "The overexpression of DKK3/REIC inhibits tumor growth in prostate cancer, melanoma and hepatocellular carcinoma." (PMID 19247449, 2009). "In mouse cancer models, DKK3 has proved a promising therapeutic agent capable of repressing tumour progression, for example, in testicular germ cell cancer and prostate cancer." (PMID 18826564, 2008). "A study utilizing the DNA methyltransferase (DNMT) inhibitor decitabine to treat PC3 prostate cancer cells resulted in the demethylation of the DKK3 promoter, leading to elevated DKK3 expression and the inhibition of TGF-β/Smad-dependent transcriptional activity." (PMID 40600050, 2025). "Notably, reducing the expression of DKK3 increases Wnt signaling activity in breast cancer cells and potentiates the effect of β-catenin in prostate cancer cells." (PMID 36497305, 2022). "Furthermore, a recent research investigation has documented that activation of DKK3 can dampen prostate cancer development." (PMID 35303365, 2022). "Admittedly, DKK3 functions as tumor suppressor and loss of DKK3 function is associated with poorer outcomes in DKK3 non-expressing tumors, such as prostate cancer and renal cancers, which is also confirmed by the analyses using by data in TCGA." (PMID 36376957, 2022). "Ectopic DKK3 expression also induces apoptosis in prostate cancer cells." (PMID 36497305, 2022). "Interestingly, in prostate cancer cells, DKK3 expression induced cellular quiescence through the activation of p38 MAPK signaling pathway." (PMID 34022894, 2021). "However, one study revealed high DKK-3 protein levels in seminal plasma of prostate cancer patients." (PMID 34451907, 2021). "Among Wnt agonists, DKK3 was demonstrated to be regulated by miR-183 in prostate cancer." (PMID 34769207, 2021). "Furthermore, the LINC00261/GATA6/DKK3 axis plays a crucial role in the development and prostate cancer progression; LINC00261-targeted GATA6 suppressed the proliferation, migration, invasion and angiogenesis of prostate cancer by promoting activation of DKK3." (PMID 33013201, 2020). "LINC00261, GATA6 as well as DKK3 expression in prostate cancer was down-regulated." (PMID 33013201, 2020). "DKK3 could induce cellular quiescence in prostate cancer cells through activating the p38MAPK signaling pathway." (PMID 33013201, 2020). "Overexpression of LINC00261 inhibited prostate cancer cells proliferation, migration, and invasion as well as angiogenesis, which could be reversed by silencing DKK3." (PMID 33013201, 2020).
prostate carcinoma (continued). "In short, LINC00261 overexpression inhibited the proliferation, migration, invasion and tube formation of prostate cancer cells which could be reversed by DKK3 silencing." (PMID 33013201, 2020). "LINC00261, GATA6, and DKK3 were poorly expressed in prostate cancer." (PMID 33013201, 2020). "We will further explore the effects of DKK3 on prostate cancer by using whole-genome approaches." (PMID 33013201, 2020). "Furthermore, a recent study has already established a relationship between DKK3 and prostate cancer, DKK3 was down-regulated in prostate cancer cells where it inhibited tumor growth, proliferation and migration of prostate cancer." (PMID 33013201, 2020). "In addition, a recent study has shown that induction of DKK3 can inhibit prostate cancer development." (PMID 33013201, 2020). "Given the tumor-inhibitory properties of Dkk-3, we hypothesized that the stromal expression of Dkk-3 is protective and may prevent prostate cancer initiation or progression." (PMID 29858602, 2018). "Dickkopf-3 (Dkk-3) is a secreted glycoprotein that is downregulated in prostate cancer." (PMID 29858602, 2018). "DKK3 is downregulated by promoter methylation in many types of cancer, including prostate cancer." (PMID 29843383, 2018). "Several studies have reported downregulation of Dkk-3 in prostate cancer." (PMID 29858602, 2018). "Ectopic expression of Dkk-3 rapidly induces apoptosis in prostate cancer cells." (PMID 29843383, 2018). "This might imply a link between the effects of Dkk-3 on prostate cancer cell proliferation and on TGF-β signaling." (PMID 29843383, 2018). "Dkk-3 is abundant in the normal prostate epithelium and downregulated in prostate cancer." (PMID 29858602, 2018). "The underexpression of REIC/Dkk-3 in CHP-1 suggests that the lack of this protein causes the androgen-independency in canine prostate cancer." (PMID 28599655, 2017). "Additionally, reporter assays revealed that canine REIC/Dkk-3 restored AR signalling in both human and canine androgen-independent prostate cancer cells." (PMID 28599655, 2017). "Our recent study revealed that the overexpression of REIC/Dkk-3 in the human androgen-independent prostate cancer cell line PC3 upregulates AR signalling and restores the expression of prostate specific antigen (PSA) by interfering with the dimerization of SGTA." (PMID 28599655, 2017). "In addition, we demonstrated that the overexpression of the canine REIC/Dkk-3 protein upregulates AR signal transduction in both canine and human androgen-independent prostate cancer cell lines." (PMID 28599655, 2017). "If DKK3 regulates the growth of normal and cancerous prostate cells, the variation in DKK3 activity may be important in the onset and progression of prostate cancer." (PMID 26689513, 2015). "In support of the hypothesis that DKK3 functions in prostate as a tumor suppressor, overexpression of DKK3 suppresses cell growth and the invasive capacity of prostate cancer cell lines." (PMID 26689513, 2015). "DKK3 was proposed to function as a tumor suppressor since it was found to be down-regulated in a number of malignancies including kidney, bladder, lung, pancreas and prostate cancer." (PMID 20976069, 2010). "Indeed, decitabine induces DKK3 expression in prostate cancer and AML cells." (PMID 36497305, 2022). "However, the role of DKK3 that regulating by LINC00261 in the development of prostate cancer was unknown." (PMID 33013201, 2020). "Finally, we collected the prostate cancer data from the database and found that the expression of DKK3 was negatively correlated with the expression of LINC00261, and that patients with high expression of LINC00261 had a poor prognosis, which was consistent with our experimental results." (PMID 33013201, 2020).